SOCS3 (suppressor of cytokine signaling 3)
Diseases named in the same sentence as SOCS3 in open-access papers (continued):
Sharing a sentence is not in itself a finding about the gene and the disease.
Obesity (continued). "For instance, during influenza virus infection in diet-induced obesity, the CD8+ T cell memory was depleted and pulmonary SOCS3 mRNA expression was induced when compared to infected lean mice." (PMID 29868503, 2018). "Consistently, increased SOCS3 expression in POMC neurons results in impaired STAT3 signaling with subsequent leptin resistance and obesity." (PMID 28270795, 2017). "The high circulating levels of leptin during obesity lead to the chronic activation of intracellular JAK-STAT3 signaling, which further induces the expression of SOCS3." (PMID 29025435, 2017). "Deletion of SOCS3 in hypothalamic neurons enhances leptin sensitivity, reduces appetite, and protects from diet-induced obesity; while overexpression of SOCS3 in proopiomelanocortin (POMC) neurons leads to hyperphagia and obesity." (PMID 27812350, 2016). "There is reduced skeletal muscle IL-6 receptor expression in obesity and abnormal STAT3/suppressor of cytokine signaling 3 (SOCS3) signaling, and attenuated IL-6 induced AMPKα2 activation with T2D." (PMID 23675368, 2013). "Increased SOCS-3 expression in POMC neurons inhibits activation of signal transducer and activator of transcription (STAT)-3 and results in hyperphasia and obesity." (PMID 23696840, 2013). "Consistently, SOCS3 overexpression in POMC neurons leads to leptin resistance and mild obesity." (PMID 41251447, 2025). "However, in obesity, chronically elevated leptin levels induce SOCS1 and SOCS3, which in turn inhibit JAK2 phosphorylation and downstream STAT1/STAT2 activation." (PMID 40844207, 2025). "Additionally, upregulation of FTO/CX3CL1 and suppressor of cytokine signaling 3 (SOCS3) in the hypothalamus impairs leptin- and signal transducer and activator of transcription 3 (STAT3) signaling, resulting in leptin resistance and obesity." (PMID 39125332, 2024). "As was shown from studies in high-fat diet fed mice, in obesity, important mediators in the observed leptin resistance in AgRP neurons are JNK, NF-kB, suppressor of cytokine signaling 3 (SOSC3), protein tyrosine phosphatase 1B (PTP1B, also known as polypyrimidine tract binding protein 1), and PKC." (PMID 39728000, 2024). "Additionally, we further demonstrated the inhibitory effects of reticuline on the JAK2/STAT3/SOCS3 and p38 MAPK/NF‐κB signaling pathways in the HFD and OVA‐induced obesity‐related asthma models." (PMID 38286741, 2024). "In line with our data, increased basal transcript levels of SOCS3 but not SOCS1 were found in peripheral blood mononuclear cells of individuals with obesity as compared with their non-obese counterparts." (PMID 36609306, 2023). "Our results showed that neither SOCS1 methylation level nor SOCS3 methylation level alter in SAT women with obesity in comparison with ones with normal weight." (PMID 36609306, 2023). "As for the analysis of promoter methylation, it was found that SOCS1 and SOCS3 methylation were not significantly different between the individuals with obesity and normal weight (P-value = 0.45 and P-value = 0.89)." (PMID 36609306, 2023). "As for the analysis of promoter methylation, it was found that SOCS1 (P-value = 0.45 and Z-score = -0.78) and SOCS3 methylation (P-value = 0.89 and Z-score = -0.156) were not significantly different between the individuals with obesity and normal-weight." (PMID 36609306, 2023). "It has also been shown that SOCS3 knockout mice had improved leptin sensitivity through increased hypothalamic STAT3 phosphorylation and POMC induction, while showing resistance to high-fat diet-induced obesity." (PMID 37571301, 2023). "Our findings point to alterations of SOCS1 and SOCS3 transcript levels, but not promoter methylation levels in subcutaneous adipose tissues from women with obesity." (PMID 36609306, 2023).
Obesity (continued). "The expression levels of LEPRB, SOCS-3, JAK2, and STAT3, and the key targets in the JAK2-STAT3 signaling pathway in liver and adipose tissue of mice in each group, were analyzed to verify the mechanism of HJJPD in the treatment of simple obesity." (PMID 35529938, 2022). "In non-pregnant individuals, SOCS3 DNA methylation has been previously shown to be inversely related to body weight and to modulate the impact of overall stress on obesity." (PMID 35631263, 2022). "SOCS3 negatively regulates the JAK-STAT signaling pathway and limits IFN production by downregulating interferon stimulated gene (ISG) transcription in individuals with obesity." (PMID 36466818, 2022). "Of note, one of the SOCS3 CpGs identified in this study, cg18181703, was also identified in a recent large-scale EWAS of BMI, and methylation at this CpG was shown to interact with cumulative adverse life stress to influence BMI and obesity." (PMID 35665255, 2022). "In obesity, there is also an increase in the synthesis and release of IL-6, which acts on STAT3, favoring the activation of the suppressor of cytokine signaling 3 (SOCS3)." (PMID 35277049, 2022). "Moreover, the increased SOCS3 in the hypothalamus in turn suppresses JAK2/STAT3 signaling pathway, which forms leptin resistance, leading to hyperleptinemia and obesity." (PMID 36270984, 2022). "This is consistent with well-established concept of chronic inflammation in obesity and the overexpressive SOCS3 as a negative feedback regulator." (PMID 34489970, 2021). "However, the interaction between SOCS3 and WNK4 axis in regulating VILI in the context of obesity warrants further investigation." (PMID 34489970, 2021). "Meanwhile, SOCS3 acting as a negative feedback inhibitor of leptin signaling presented a potential therapeutic prospect for obesity-related OA." (PMID 34457118, 2021). "Conversely, no increase in the IFN-α response has been observed in the non-obese volunteers, thus confirming the key role of SOCS3 in inhibiting IFN-I after TLR stimulation in obesity." (PMID 33430520, 2021). "Despite the lack of tissue specificity in hypothalamic SOCS3 knockdown-mediated protection against diet-induced obesity, collectively these studies firmly implicate SOCS3 as a molecular mediator of ARC leptin resistance." (PMID 34613819, 2021). "In these regions, leptin signaling is mediated by the JAK2/Stat3 pathway, in which several negative regulators of JAK2, including SOCS3 and PTP1B, have been reported to promote obesity, supporting the notion that JAK2 inhibitory molecules increase risk for leptin resistance and obesity." (PMID 32630697, 2020). "In obesity and T2D subjects, the IL-6 signaling pathway in muscle cells has an abnormal function because there is a reduction in the expression of IL-6 receptor and also an abnormal STAT3/suppressor of cytokine signaling 3 (SOCS3) in adipose tissue." (PMID 30691224, 2019). "In our study, SOCS3 gene expression was up-regulated in both the VAT and SAT of obesity patients." (PMID 30619480, 2018). "Unexpectedly, SOCS3 upregulation in ObRb-expressing neurons does not lead to obesity, but rather a more lean phenotype." (PMID 28270795, 2017). "Furthermore, previous studies demonstrated that SOCS3 and PTP1B levels were elevated in a mouse model of obesity, suggesting the involvement of SOCS3 and PTP1B in leptin resistance with obesity." (PMID 27375555, 2016). "SOCS3 also exerts its negative effect on muscle by sequestering leptin, leading to the leptin resistance in skeletal muscle observed in obesity." (PMID 27746742, 2016). "Mice lacking SOCS3 in this particular population of neurons are protected from the development of diet-induced obesity and maintain central leptin sensitivity." (PMID 24600449, 2014). "Thus, SOCS3 and tyrosine phosphatases play multiple roles in HFD-induced obesity." (PMID 40690443, 2025).
Obesity (continued). "In addition, the inhibitor of cytokine signaling 3 (SOCS3) and/or protein tyrosine phosphatase 1B (PTP1B) appear to share the suppressive effects on insulin and leptin signalings that are frequently observed in obesity." (PMID 38921683, 2024). "It is likely that Slug may have additional epigenetic targets involved in leptin resistance and obesity, such as positive regulators, like Sh2b1, and negative regulators, like SOCS3 and PTP1b, of LepRb signaling." (PMID 36512408, 2023). "This study shows that overexpression of the G0S2 gene aggravates liver insulin resistance of mice through upregulating P-Foxo1, Socs3, and Ptpn1 and downregulating Gstp1 and Ppar-γ, which demonstrates that G0S2 may be a potential target gene for the treatment of NAFLD, obesity, and diabetes." (PMID 37033250, 2023). "Increased SOCS3 expression as a result of SARS-CoV-2 infection could therefore further impair leptin signaling and negatively influence the immune response in patients suffering from obesity." (PMID 33920604, 2021). "Inhibition of IL6 and SOCS3 and facilitation of CNTF could serve as a favorable strategy to enhance insulin action and improve glucose homoeostasis, which are of importance for treating obesity-related disorders for chickens." (PMID 32106651, 2021). "As many PRRs and negative regulators of PRR signaling are themselves induced by cytokines or PAMPS and DAMPS, obesity may increase expression of PRRs, therefore sensitizing cells to viral PAMPs and DAMPS, while increasing expression of negative regulators such as SOCS3." (PMID 34777390, 2021). "In addition, previous studies found that exogenous leptin treatment in mice induced higher levels of SOCS3 in the hypothalamus, and mice with obesity induced by a high-fat diet do not respond to exogenous leptin treatment due to leptin resistance." (PMID 32846917, 2020). "SOCS3 upregulation and altered systemic leptin levels could be responsible for the reduced type I IFN response as well as other immune dysfunction relevant to T cells and B cells in people with obesity." (PMID 31726661, 2019). "Yet, whether adipocytes exhibit leptin resistance is not unclear: several papers concluded that obesity induces leptin resistance in whole AT,46,47 characterized by decreased pSTAT3 levels and elevated SOCS-3 expression." (PMID 30676227, 2019). "In ANOVA modeling, leptin concentrations in SF and SOCS-3 expression in cartilage significantly explained levels of SF MMP-1 and MMP-3 in the obese but not in the non-obese group pointing to obesity-related association of leptin and SOCS-3 in OA pathophysiology." (PMID 27716333, 2016). "However, expression of hypothalamic Socs-3 did not rise with increasing obesity and leptin levels, as measured 2, 6, and 9 wk p.i.." (PMID 23554574, 2013). "Since reduced SOCS3 expression in the Arc would tend to increase signaling by leptin and other cytokines to promote leanness, the regulation of hypothalamic SOCS3 expression by STAT5 is also unlikely to underlie the obesity of the Stat5fl/fl; Nestin-Cre mice." (PMID 18286195, 2008). "Our results do not suggest a major role of the analysed SNPs in SOCS3 in early onset obesity." (PMID 17445271, 2007). "Thus, SOCS3 upregulation and altered systemic leptin levels could be responsible for the reduced IFN-I response as well as for other immune dysfunctions relevant to T and B cells in people with obesity." (PMID 33430520, 2021). "In obesity, however, persistent hyperleptinemia induces negative feedback: inflammatory cytokines such as TNF-α and IL-6 elevate SOCS3 expression, limiting STAT3 phosphorylation and nuclear translocation, while PTP1B dephosphorylates JAK2." (PMID 41588470, 2026). "Mice lacking SOCS3 in the brain or specifically in POMC neurons exhibit enhanced leptin sensitivity and are resistant to diet-induced obesity." (PMID 41516046, 2025).
Obesity (continued). "In nonobese mice, SOCS3 augmentation (CD + hesperetin) resulted in a trend toward WNK4 upregulation, albeit to a much lesser extent compared with the effect of obesity itself." (PMID 34489970, 2021). "Circulating leptin levels are increased in obesity and, with prolonged exposure, leptin can induce its own negative feedback loop via STAT3-dependent SOCS3 accumulation." (PMID 35111163, 2021). "Further studies confirmed their findings and identified that resveratrol alleviating obesity-related osteoarthritis via alleviating JAK2/STAT3 signaling pathway, which independent of SOCS3." (PMID 34215299, 2021). "However, in chronic inflammatory states such as those that may occur in obesity and NAFLD, IL-6 acts as a proinflammatory cytokine, reducing myogenesis by inhibiting insulin-like growth factor (IGF)-1 activity via activation of suppressor of cytokine signaling-3 (SOCS-3)." (PMID 33424768, 2020). "It was found that unlike SOCS3, which disclosed an elevating expression pattern, the expression level of SOCS1 was lower in the women with obesity as compared with their non‐obese counterparts (P-value = 0.03 for SOCS1 transcript level and P-value = 0.011 for SOCS3 transcript level)." (PMID 36609306, 2023). "In another study of obesity-related KOA, Jiang found that RES attenuated obesity-related KOA by attenuating the janus kinase 2 (JAK2)/STAT3 signaling pathway independent of the suppressor of cytokine signaling 3 (SOCS3) pair." (PMID 35959426, 2022).
breast cancer (82 papers, 2003 to 2025). A primary or metastatic malignant neoplasm involving the breast. "We previously summarized the role of SOCS3 in several types of tumors, and numerous experiments have also confirmed the association between SOCS3 and different types of cancer, including breast cancer, colorectal cancer, and glioblastoma." (PMID 35600392, 2022). "In large and locally advanced breast cancer, high number of suppressor of cytokine signaling 3+ (SOCS3+) TAMs (M1 macrophages) were associated with a pathological complete response after neoadjuvant chemotherapy." (PMID 36207349, 2022). "SOCS3 expression is decreased in breast cancer tissues compared with normal tissues, and a lower level of SOCS3 is associated with poor clinical outcomes." (PMID 34120621, 2021). "Significantly, miR-203a-3p suppresses expression of SOCS3 that has been shown to be closely associated with lymph node metastasis in breast cancers." (PMID 34316330, 2021). "Loss of SOCS3 expression has also been recently associated with increased risk of recurrence of breast cancer." (PMID 23028842, 2012). "Furthermore, we analyzed the immunosuppressive capacity of eMDSCs in 4T1 mammary tumor-bearing mice and found eMDSCs impaired T cell immunity significantly in SOCS3 deficiency-dependent manner by activating the JAK/STAT signaling pathway." (PMID 36329699, 2022). "For example, circRNA transcriptional adaptor 2A (circTADA2A) has been shown to modulate the microRNA-203a-3p/suppressor of cytokine signaling 3 (SOCS3) axis in breast cancer, thereby suppressing cell proliferation, migration, and invasion." (PMID 40728965, 2025). "Identifying key signaling pathways and regulatory molecules, such as PIAS3, PIP, STAT5, and SOCS3 in breast cancer (BC) cells, can provide valuable insights into the mechanisms of the disease and potentially lead to the development of targeted therapies." (PMID 40003884, 2025). "Xu and colleagues have reported that circTADA2As repress breast cancer progression and metastasis by targeting miR-203a-3p/SOCS3 axis." (PMID 38635778, 2024). "KLF14 suppressed breast cancer cell invasion and M2 macrophage polarization through modulating SOCS3/RhoA/Rock/STAT3 signaling." (PMID 38143751, 2023). "In breast cancer, SOCS3 inhibited tumor metastasis and tumor cell proliferation regulated by multiple non-coding RNA." (PMID 37025997, 2023). "In general, it is believed that SOCS3 can inhibit tumors, including breast cancer and ovarian cancer." (PMID 36690663, 2023). "The previous report has shown that circ_0001785 can inhibit the proliferation, migration, and invasion of breast cancer cells, either in vitro or in vivo, by up-regulating SOCS3 through sponging miR-942." (PMID 37794449, 2023). "It has a potential treatment to regulate the expression of SOCS3 causing JAK/STAT inhibition in bone‐associated inflammatory diseases, influenza, and breast cancer." (PMID 36217678, 2023). "Another mechanism of involvement of DANCR in the pathogenesis of breast cancer is mediated through enhancement of the EZH2 binding to the promoter of SOCS3, which results in suppression of expression of SOCS3." (PMID 35590326, 2022). "For breast cancer and leukemia patients with T-cell dysfunction, the cohort with high SOCS3 expression possessed a higher survival time." (PMID 35600392, 2022). "The results showed that SOCS3 was downregulated in most The Cancer Genome Atlas (TCGA) cancer datasets but was highly expressed in brain tumors, breast cancer, esophageal cancer, colorectal cancer, and lymphoma." (PMID 35600392, 2022). "Our research indicated that ovarian and breast cancer patients with high SOCS3 expression levels were resistant to chemotherapy; however, GBM and colorectal cancer patients were more sensitive to chemotherapy." (PMID 35600392, 2022).